PCDH20 (protocadherin 20)
Diseases named in the same sentence as PCDH20 in open-access papers (continued):
Sharing a sentence is not in itself a finding about the gene and the disease.
tumor (12 papers, 2017 to 2024). "The expression of PCDH20 was restored after the addition of DNMT inhibitors to the corresponding tumor cell lines." (PMID 38327746, 2024). "PCDH20 functions as a calcium-coated protein that facilitates cellular adhesion and metastasis of tumor cells." (PMID 36248995, 2022). "Alterations of these PCDHs can occur through several oncogenic pathways; for example, PCDH20 functions as a tumor-suppressor gene by antagonizing the Wnt/β-catenin signaling pathway in HCC." (PMID 36230503, 2022). "PCDH20 has obvious inhibitory effect on tumor proliferation in vivo, so we carried out IHC to assess Ki67 variation in PCDH20-overexpressing cell compared with vector group." (PMID 36248995, 2022). "The expression of PCDH20 mRNA in tumor tissues was reduced compared with that of adjacent tissues based on qPCR." (PMID 36248995, 2022). "PCDH20 exerted anti-tumor effects by MAP3K9 downregulation, which suppressed AKT/β-catenin signaling in ESCC cells." (PMID 36248995, 2022). "The tumor-suppressor gene PCDH20 through the Wnt/β-catenin signaling pathway acts inhibiting cell proliferation and cell migration." (PMID 35027621, 2022). "For instance, PCDH8 and PCDH20 are considered tumour suppressors, while PCDH11Y functions as an oncoprotein." (PMID 35864095, 2022). "We found that compared with the control group, the weight and volume of tumor decreased significantly in cells with ectopic expressing PCDH20." (PMID 36248995, 2022). "Pcdh20 codes for a protocadherin, a homophilic cell-adhesion protein, and has been suggested to function as a tumour-suppressor gene." (PMID 31320724, 2019). "As a tumor suppressor gene, protocadherin 20 (PCDH20) is a member of the cadherin superfamily." (PMID 38327746, 2024). "PCDH20 anti-tumor functions in various tumor have been identified." (PMID 36248995, 2022). "Nude mice tumorigenicity was used to assess PCDH20 anti-tumor effect in vivo." (PMID 36248995, 2022). "PCDH10, PCDH17 and PCDH20 expression levels were downregulated in this neoplasm." (PMID 33369468, 2020). "The expression levels of PCDH20 were also tested by quantitative real-time polymerase chain reaction and western blot in 50 patients; and we found that the mean level of PCDH20 expression in the tumor tissues was significantly lower than that in the PC tissues." (PMID 27935871, 2017). "Thus, PCDH20 may have several tumor suppression functions, potentially contributing to tumor growth control, signal transduction, and cell-cell adhesion." (PMID 33369468, 2020). "In addition, according to a study, PCDHs located on chromosome 13q21, such as PCDH8, PCDH9, PCDH17, and PCDH20, may be involved in tumor suppression." (PMID 33369468, 2020). "In our cohort, sex, PCDH20, AFP, and tumor number were found to be four crucial independent prognostic factors for HCC." (PMID 27935871, 2017). "Importantly, some the genes upregulated upon ZNF714 knockdown (PCDH20, STRA6, ARNT2, TIMP3) were previously shown to function as tumor suppressors." (PMID 37958512, 2023).
cancer (7 papers, 2016 to 2024). A tumor composed of atypical neoplastic, often pleomorphic cells that invade other tissues. "There is a paucity of data regarding the underlying mechanism of PCDH20 activity in the cancer setting." (PMID 27935871, 2017). "It was previously shown that expression levels of protocadherins, such as PCDH8, PCDH10, and PCDH20, were downregulated by promoter methylation in various carcinomas, which were strongly associated with advanced cancer or poor outcome." (PMID 27351130, 2016). "The previous studies have shown that the expression of PCDH20 was frequently decreased or silenced in multiple cancers, primarily attributed to the methylation of the promoter region." (PMID 38327746, 2024). "However, the associations of other genes used in our model with ICI efficacy have not been reported, although some of them have been found to play critical roles in cancer, such as COL5A2, FAT2, ITPR3, PCDH20, and UTRN." (PMID 35557959, 2022).
PCDH20 also shares sentences with these, for which no sentence is quoted: breast carcinoma (1 paper); cervical cancer (1); hypo-pharyngeal squamous cell carcinoma (1); leiomyosarcoma (1); schizophrenia (1).